HIF1A (hypoxia inducible factor 1 subunit alpha)
Diseases named in the same sentence as HIF1A in open-access papers (continued):
Sharing a sentence is not in itself a finding about the gene and the disease.
tumor (continued). "Based on low basal levels of HIF-1α in EPLC-272H and high levels in H1339 tumor cells, a higher sensitivity towards Hsp90 inhibition was expected for EPLC-272H cells." (PMID 22347438, 2012). "They found that overexpression of miR-21 in DU145 cells increased the expression of HIF-1α and VEGF, and induced tumor angiogenesis." (PMID 22295063, 2012). "In the present study we have demonstrated that in HT1080 cells, hypoxia up-regulates the expression of NRP-1 in a HIF-1α-dependent manner and, more importantly, this up-regulated NRP-1 plays a deterministic role in their vasculogenic mimicry and tumour growth." (PMID 23185562, 2012). "Over-expression of miR-21 in DU145 cells increased the expression of HIF-1α and VEGF, leading to increased tumor angiogenesis." (PMID 22952749, 2012). "In the same study, the authors found hypoxic tumor regions to be co-localized with regions of high tCho, which possibly occurred through the up-regulation of CHKA by HiF-1α." (PMID 22277092, 2012). "Apigenin suppressed tumor angiogenesis by downregulating VEGF, a proangiogenic protein regulated by HIF-1α." (PMID 22844340, 2012). "To verify if ROS affect HIF-1α transcriptional activity we measured VEGF-A mRNA, one of the main HIF-1α target genes and a key factor for de novo tumour angiogenesis." (PMID 23144690, 2012). "HIF-1α (45%) was more frequently expressed than HIF-2α (30%), but clinicopathological variables representing tumor aggressiveness correlated more often with HIF-2α, than HIF-1α." (PMID 22454562, 2012). "We noticed that VEGFA, HIF1A, SOX4, SOX9, MMP2, TGFB1 genes are overexpressed together with S6K1 in all 4 tumour types investigated." (PMID 22570651, 2012). "During serum deprivation, miR-17 prolonged tumor cell survival, induced angiogenesis and promoted stem-like cell aggregation by repressing expression of MDM2 and PTEN and modulating HIF-1α levels." (PMID 23391506, 2012). "It is possible that nicotine promotes HIF-1α protein accumulation in NPC cells, and then HIF-1α induces the expression of the related genes which are involved in tumor cell proliferation." (PMID 22952803, 2012). "Hypoxia-induced HIF-1α stabilization leads to the expression of various angiogenic factors, such as VEGF, and chemotactic factors, such as SDF-1α and CSF-1, by hypoxic tumor cells." (PMID 22888475, 2012). "The expression levels of HIF-1α and VEGF in the tumor sections were also higher in miR-SCR control group than those in miR-128-expressing group." (PMID 22442669, 2012). "Over-expression of both HIF1A and LOXL2 was observed only in the surgically resected tumor tissues obtained from different cases." (PMID 21533028, 2011). "Taken together, miR-21 inhibited PTEN expression, which in turn decreased AKT and ERK activation for inhibiting HIF-1α and VEGF expression, thus inducing tumor angiogenesis." (PMID 21544242, 2011). "We found that overexpression of miR-21 in DU145 cells increased the expression of HIF-1α and VEGF, and induced tumor angiogenesis." (PMID 21544242, 2011). "Western blot analysis showed that IκBαM overexpression decreased the expressions of HIF-1α and VEGF in similar sized tumours." (PMID 21119667, 2011). "Based on reports describing a role for HIF-1α and VEGF in determining blood vessel morphogenesis, including lumen formation, we hypothesized that a differential pattern of expression of these genes might underlie the different vascular morphologies in this tumor model." (PMID 22235379, 2011). "A recent report in this journal on expression of GAPDH in tumor and non-tumor cell lines clearly demonstrated that GAPDH expression increases under hypoxic conditions in a cell-type specific manner, likely due to HIF-1α induction." (PMID 22023915, 2011). "ILK contributes to tumour progression by increasing the expression of VEGF via the activation of PKB/Akt and HIF-1α, thereby stimulating angiogenesis." (PMID 21426571, 2011).
tumor (continued). "Since HIF-1α can promote the expansion of CD133-positive gCSCs, it is possible that hypoxia induces a feed-forward mechanism of tumor-mediated immunosuppression." (PMID 21283755, 2011). "In vitro we used microarray to screen out the angiogenic genes regulated by HIF-1a and tested their expression level in CAM transplantation tumor by RT-PCR and Western-blot analysis." (PMID 21843314, 2011). "Consistent with tumor data, we determined that the subgroup 7 cell line (AU565) has significantly higher mRNA levels of HIF1A (HIF-1α) and EPAS1 (HIF-2α) when compared to the subgroup 10 cell line HCC202." (PMID 21672245, 2011). "Tumor weight was found to be significantly reduced in ENO1 and HIF1α siRNA treated mice with respect to its control group." (PMID 21754983, 2011). "While this is apparently at odds with the frequently observed upregulation of HIF-1α in cancer, it is consistent with emerging evidence for differential effects of HIF-1α and HIF-2α in tumor biology." (PMID 22014577, 2011). "Here, HIF-1α-induced BNIP3 expression presumably led to enhanced mitophagy, and when autophagy was inhibited chemically, increased tumor cell death occurred." (PMID 22190938, 2011). "Inhibition of HIF-1α, CAIX, LOX, or CXCR4 to reduce the development and growth of tumour metastases represent rational therapeutic strategies to disrupt the metastatic process." (PMID 22128892, 2011). "In rapidly growing tumors, local hypoxic conditions induce the expression of transcription factor HIF-1α, which in turn activates the expression of VEGF in tumor cells." (PMID 20429953, 2010). "The factors HIF-1α and ATF3 are both induced by hypoxia and other cellular stressors, and both transcription factors regulate the expression of multiple genes during tumor progression and metastasis." (PMID 21129190, 2010). "In this study, necrotic lesions were detected in hypoxic areas of OCUM-12 tumours but were rarely found in OCUM-12/Hypo tumours, whereas pimonidazole, CA9, and HIF-1α staining revealed both areas to be hypoxic." (PMID 20145613, 2010). "Accumulation of HIF-1a at the protein level leads to continuous activation of downstream target genes (e.g., VEGF and PDGF), which were all upregulated in our tumor sample panel." (PMID 21253009, 2010). "Based on these studies, we suggest that combinations of HIF-1α, CXCR4, and VEGF expression in tumor tissue will be useful for predicting clinicopathologic significance and tumor metastasis." (PMID 20953377, 2010). "HIF-1α is a critical transcription factor for the regulation of vascular endothelial growth factor (VEGF), a potent inducer of tumor angiogenesis and metastasis." (PMID 20723262, 2010). "In the current study there was strong nuclear immunoreactivity for HIF-1α and HIF-2α in the control tumour cases and brain tissue from a fatal diffuse ischaemic-hypoxic injury." (PMID 20716170, 2010). "Our finding that THL can inhibit cancer cells to express HIF-1α and to secrete VEGF-A is important in terms of suppression of tumor angiogenesis." (PMID 20429953, 2010). "We recently reported a novel way to downregulate HIF-1α through transcriptional repression by HIPK2, a potential biomarker for tumor growth." (PMID 21179202, 2010). "To confirm that impaired NE tumor formation is due to Siah's effect on HIF, we transfected TRAMP cells with a Siah inhibitory peptide and observed reduced HIF-1α levels and inhibited tumor formation in nude mice." (PMID 21037926, 2010). "The blocking of HIF-1α and VEGF-A expression in tumor cells can thus lead to inhibition of neovessel formation in tumors." (PMID 20429953, 2010). "Overall, the regulation of HIF-1α/HIF-1β and androgen receptor suggests a role of miR-101 in tumor progression and normal prostate development." (PMID 20478051, 2010).
tumor (continued). "HIF-1α and VEGF were used as the endpoints of the present study because either or both can elicit an array of effects, from initiating angiogenesis to tumor metastasis." (PMID 20723262, 2010). "Using HCT116 cells, a colon carcinoma, deleted for HIF-1α, we then silenced PHD2 and implanted these cells as tumours." (PMID 20461086, 2010). "Endothelial cell KIT expression is frequent also in clear‐cell renal cell carcinomas, where HIF‐1α and VEGFR‐mediated molecular mechanisms likely have an important role in tumor pathogenesis." (PMID 20030644, 2010). "In this study, we investigated HIF-1α, CXCR4, and VEGF expression in human colon primary tumor samples using immunohistochemistry." (PMID 20953377, 2010). "The staining of pimonidazole, HIF-1α, and CA9 was heterogeneously positive in both the OCUM-12 and the OCUM-12/Hypo tumours." (PMID 20145613, 2010). "Our data show that when HIF-1α expression is knocked down, the ability of GL261 cells to form tumor spheres is significantly reduced compared with the control cells." (PMID 20515450, 2010). "The mRNA expression of MMP7, which can degrade various ECM proteins and support the role in tumor invasion and spread in HCC, has significant correlation to HIF-1α mRNA expression in our study (r = 0.593)." (PMID 19948069, 2009). "Inhibition of HIF-1α or TGF-β with these inhibitors also decreased osteolysis, reduced tumor burden, and enhanced survival of mice with bone metastases." (PMID 19727403, 2009). "In a second pharmacologic approach, we inhibited HIF-1α and TGF-β signaling systemically using small molecule inhibitors to target both the tumor cells and the bone microenvironment." (PMID 19727403, 2009). "Together, our in vitro and in vivo results suggest that HIF-1α promotes bone metastases by regulating factors such as CXCR4, which promotes tumor cell homing to bone and VEGF, which promotes angiogenesis." (PMID 19727403, 2009). "Since HIF-1α knockdown in vitro resulted in decreased mRNA expression of the angiogenic factor VEGF, we analyzed tumor angiogenesis in vivo by staining for the endothelial cell marker CD31." (PMID 19727403, 2009). "For example, RAW 264.7 cells stimulated with tumor cell CB up-regulated several angiogenic factors (VEGF-A, HIF1α and TGF-β) and chemoattractants (CXCL12 and CXCL2)." (PMID 19696929, 2009). "The accentuated expression at the invading edge together with the in vitro requirement of HIF-1α for migration, invasion and adherence argues for a pivotal role of HIF-1α in local invasion and, ultimately, systemic tumour spread." (PMID 19223895, 2009). "We inhibited HIF-1α and TGF-β pathways in tumor cells by shRNA and dominant negative receptor approaches." (PMID 19727403, 2009). "pFAK expression in circulating tumor cells was detected in 92% of patients whereas expression of VEGF, VEGF2 and HIF-1α was observed in 62%, 47% and 76% of patients, respectively." (PMID 19919679, 2009). "The expression of HIF-1α, VEGF-A and VEGF-C in carcinoma cells was compared to tumor variables that represent prognostic factors in CRCC: nuclear grade, tumor size, Ki67 proliferative index and pathologic stage." (PMID 19302703, 2009). "Mounting experimental evidence indicates that there are distinct functions for HIF-1α and HIF-2α during tumor growth, and that there is little redundancy between the two α subunits." (PMID 20046830, 2009). "Such multiple regulation relationship among miR-20b, HIF-1α and VEGF therefore keep tumor cells to adapt different oxygen concentration for survival." (PMID 19893619, 2009). "The inhibition of miR-20b increased the protein levels of HIF-1α and VEGF in normoxic tumor cells; the increase of miR-20b in hypoxic tumor cells, nevertheless, decreased the protein levels of HIF-1α and VEGF." (PMID 19893619, 2009). "The levels of expression of HIF-1α and VEGF in tumor cells were both higher than those in normal cells." (PMID 20003271, 2009).
tumor (continued). "Knockdown of HIF-1α in MDA-MB-231 cells decreased VEGF expression in vitro, and inhibited tumor angiogenesis at sites of bone metastasis in vivo, as demonstrated by CD31 staining for endothelial cells." (PMID 19727403, 2009). "Since hypoxia-inducible factor-1α (HIF-1α) and vascular endothelial growth factor (VEGF) play an important role in angiogenesis and tumor progression, the purpose of the current study was to investigate their expression in CTCs." (PMID 19919679, 2009). "Hypoxic tumour cells were reoxygenated 6 h postirradiation, leading to von Hippel-Lindau (VHL)-dependent proteolysis of HIF-1α and a resultant decrease in HIF-1 activity." (PMID 19223896, 2009). "Many different mechanisms can contribute to VEGF up-regulation and in this regard we have recently found that HIPK2 can regulate the HIF-1α-induced VEGF expression, inhibiting tumor angiogenesis (L.N. and G.D.O. unpublished results)." (PMID 18644116, 2008). "The novel microtubule destabilizing agent ENMD-1198 is suitable for inhibiting HIF-1α and STAT3 in human HCC cells and leads to reduced tumor growth and vascularization in vivo." (PMID 18651980, 2008). "Tumor angiogenesis and neovascularization require VEGF expression and the binding of HIF-1α to the VEGF promoter is a major pathway resulting in the induction of VEGF expression under hypoxic conditions." (PMID 18452596, 2008). "A substrate for this ubiquitin ligase is a marker of tumor hypoxia, the transcription factor HIF1A (HIF1α, hypoxia-inducible factor 1α), which stimulates angiogenesis." (PMID 19007437, 2008). "When days 0 and 7 were compared, HIF-1α mRNA increased two- and fourfold in HEP2 and Detroit 562 control tumours, respectively." (PMID 17342092, 2007). "Nuclear FIH-1 expression showed a significant positive correlation with nuclear HIF-1α expression, being twice as likely to be expressed in HIF-1α-positive tumours (P = 0.004, OR = 2.11, 95% CI = 1.26–3.52)." (PMID 18096060, 2007). "In VHL-defective renal carcinoma cells (RCC), inactivation of HIF-α proteolysis upregulates both HIF-1α and HIF-2α with global induction of HIF target gene expression, stimulating investigations of the role of the HIF pathway in tumour development." (PMID 17387348, 2007). "Inactivation of the pVHL tumour suppressor is observed in the majority of inherited and sporadic RCC leading to constitutive stabilization of both HIF-1α and HIF-2α and constitutive upregulation of HIF target gene expression." (PMID 17387348, 2007). "Recently, the expression of CXCR4 on RCC and NSCLC tumor cells was shown to be regulated by hypoxia and the VHL/HIF-1α pathway." (PMID 17083723, 2006). "We have demonstrated a cytoplasmic distribution of HIF-1α in 91% of PETs and HIF-2α in 29%, which has rarely been reported in other human tumours." (PMID 15558070, 2005). "Primary tumours and lymph node metastases with CA9 or Hif-1α expression had a higher ECP% and TCP% (P<0.003); in primary tumours, mixed/expansive growth pattern and fibrotic focus were characterised by higher ECP% (P=0.03)." (PMID 16251878, 2005). "In primary tumours, CA9 and Hif-1α expression were correlated with DEC-1 expression (P=0.05), presence of a fibrotic focus (P<0.007) and mixed/expansive growth pattern (P<0.001)." (PMID 16251878, 2005). "This pattern of expression overlaps with that of CAIX and HIF-1α, with HIF-1α located throughout tumours, showing that there is a differential pattern of localisation of hypoxia-associated molecules." (PMID 15328513, 2004). "Tumours with simultaneous LDH-5 and HIF1α (or HIF2α) overexpression, indicative of a functional HIF pathway, had a particularly aggressive behaviour." (PMID 12942121, 2003).
tumor (continued). "Conversely, a direct correlation between p21waf1 and cyclin A (P=0.03), between p16ink4A and tumour size (P=0.03), between VEGF and HIF-1α (P=0.05) and between p27kip1 and ER (P=0.05) was present only in ILC." (PMID 12402149, 2002). "Interestingly, hypoxia is correlated with tumor immunosuppression in BC, especially in TNBC and HER2E, in which less cytotoxic T-cells and NK infiltration is observed after activation of the HIF-1α (Hypoxia-Inducible Factor 1 Alpha) pathway." (PMID 41575692, 2026). "The authors suggested that JAK1 may act as a tumor suppressor, and that deletion of JAK1 activates the HIF1α pathway." (PMID 41520505, 2026). "Berberine’s anti-HIF-1α effects are accompanied by downregulation of downstream targets such as VEGF and inhibition of angiogenic and survival pathways, suggesting that it interferes with hypoxia-responsive tumor adaptation." (PMID 41614951, 2026). "Moreover, TACE‐induced hypoxia activates HIF‐1α, leading to elevated VEGF levels and promoting tumor growth." (PMID 41546425, 2026). "M2 macrophage-derived exosomal metastasis-associated lung adenocarcinoma transcript 1 (MALAT1) promotes GC progression by activating β-catenin and HIF-1α signaling to enhance glycolysis, while MALAT1 silencing suppresses tumor growth and improves chemosensitivity." (PMID 41171531, 2026). "Additionally, PAK1 has been shown to cooperate with hypoxia inducible factor 1 subunit alpha (HIF-1α), a transcription factor activated under hypoxic conditions within the tumor microenvironment." (PMID 41459112, 2026). "Furthermore, tumor tissue analysis showed that CCL2 and HIF‐1α expression levels were higher in the HFD group than in the CD group under IgG treatment, highlighting the role of the FA/HIF‐1α/CCL2 axis in cancer." (PMID 41160815, 2026). "In our study, however, tramadol-induced HIF-1α stabilization under normoxic conditions did not enhance tumor aggressiveness." (PMID 41526224, 2026). "A crucial factor in its development and treatment resistance is tumor hypoxia, which drives metabolic reprogramming (especially reconfiguration towards glycolysis), mediated to a great extent by hypoxia‐inducible factor‐“HIF‐1 alpha” (HIF‐1a)." (PMID 41521160, 2026). "Over the past years, the proteins HIF1A, EPAS1, and VEGFA have been shown to be eligible targets for anti-tumor therapies." (PMID 39888575, 2026). "Additionally, HIF-1α promotes the expression of matrix metalloproteinases such as MMP-2 and MMP-9, enzymes that facilitate tumor growth by degrading the extracellular matrix and enhancing angiogenesis." (PMID 41614951, 2026). "Moreover, Hif1α is indispensable for anti-tumor responses of both endogenous CD8 T cells and adoptively transferred tumor-specific CD8 T cells." (PMID 39925817, 2025). "In poor-prognosis luminal A tumours, for example, overexpression of CYP4F2 can metabolically suppress T-cell function, thereby undermining immune surveillance and facilitating immune evasion even in the presence of a favourable WWOX/HIF1A ratio." (PMID 41007296, 2025). "HIF1A induces CD24 expression, fostering tumor growth and spread." (PMID 41048631, 2025). "HIF-1α inhibitor PX478 did not enhance the anti-tumor effects of B+A, but HIF-1α activator DMOG reversed them." (PMID 41041327, 2025). "We crossed TFE3‐RCC mouse models with Hif1α and/or Hif2α knockout mice and found that Hif1α, rather than Hif2α, is essential for tumor development in vivo." (PMID 39807625, 2025). "By downregulating HIF-1α, COX-2, and mPGES-1, key mediators of angiogenesis and immune cell recruitment, garcinol might further shift the tumor microenvironment toward an immune-active state." (PMID 41303402, 2025). "HIF‐1α enhances the secretion of VEGF by stromal cells (such as CAFs and endothelial cells), which not only promotes angiogenesis but also activates Myc and SOX2 signalling within tumour cells." (PMID 40847555, 2025).